BRCA1 (BRCA1 DNA repair associated)
Diseases named in the same sentence as BRCA1 in open-access papers (continued):
Sharing a sentence is not in itself a finding about the gene and the disease.
ovarian carcinoma (continued). "Since no effective screening programme has yet been identified, prophylactic BSO should be advised to all high-risk women after they completed their family which will reduce the risk of ovarian cancer associated with BRCA1 or BRCA2 mutation by 70-96%." (PMID 22112691, 2011). "About 5-10% of breast and ovarian carcinomas are hereditary and most of these result from germline mutations in the BRCA1 and BRCA2 genes." (PMID 22185575, 2011). "BRCA1 mutation carriers have a 47 to 66% chance of developing breast cancer and a 35 to 46% chance of developing ovarian cancer by the age of 70." (PMID 21711529, 2011). "While mutational inactivation of BRCA1 in some familial breast and ovarian cancer is seen, a consistent pattern of BRCA1 gene mutation has not been identified in sporadic breast tumours." (PMID 21609478, 2011). "As previously noted, OCP use at any point during one's life was associated with a 50% relative risk reduction in developing ovarian cancer for BRCA1/2-mutation carriers." (PMID 22312502, 2011). "Germline mutations in BRCA1 increase the risk of breast and ovarian cancer, but the specific pathways driving breast and ovarian cancer development in BRCA1 mutants are currently unclear." (PMID 21805697, 2011). "Previous studies in Latvia have shown that the c.181T/G mutation accounts for only 6-10% of the identified BRCA1 mutations when genetic analysis had been performed in selected early-onset breast and ovarian cancers patients or in specific Latvian regions." (PMID 22032251, 2011). "The lifetime risk of ovarian cancer is 45–60% for BRCA1-mutation carriers and 11–35% for BRCA2-mutation carriers." (PMID 22312502, 2011). "Women at high ovarian cancer risk, especially those with mutations in BRCA1/BRCA2, are encouraged to undergo bilateral risk-reducing salpingo-oophorectomy (BRRSPO) prior to the natural menopause." (PMID 21654687, 2011). "In this respect we found that women at hereditary high risk of breast/ovarian cancer with a BRCA1/2 mutation had significantly lower levels of MUC1 IgG ab (p = 0.003) than age-matched healthy controls." (PMID 24212946, 2011). "This lower mutation detection rate in the families with ovarian cancers only indicates the existence of other (different from BRCA1/2) predisposing genes in hereditary ovarian cancers." (PMID 21232165, 2011). "Nanoparticle-mediated delivery of PARP1-specific siRNA inhibited growth of BRCA1-deficient mouse ovarian cancer allografts; this effect was at least in part attributed to apoptotic death of targeted cells." (PMID 21819606, 2011). "For BRCA1-mutation carriers, the risk of ovarian cancer rises sharply in the 4th decade of life and then increases progressively by approximately 10% with each subsequent decade of life." (PMID 22312502, 2011). "In this study we investigated the prevalence of the most common BRCA1 founder mutations in a population-based series of breast and ovarian cancer cases in Latvia." (PMID 22032251, 2011). "In this regard, an ideal scenario relates to genetic susceptibility to breast and ovarian cancer in women arising from a mutation in the BRCA1 gene, which is one of the most widespread genetic diseases." (PMID 21483040, 2011). "The use of OCPs was associated with significant ovarian cancer risk reduction in a case control study when used for a period of 6 or more years by BRCA1/2 carriers." (PMID 20961453, 2010). "Germ-line mutations in BRCA1 gene increase the susceptibility for the development of familial breast and ovarian cancers, indicating that BRCA1 functions as a tumor suppressor whose impaired activity would contribute to tumorigenesis." (PMID 21217819, 2010). "Women from families with a high risk of breast or ovarian cancer in which genetic testing for mutations in the BRCA1/2 genes is inconclusive are a vulnerable and understudied group." (PMID 20180951, 2010).
ovarian carcinoma (continued). "The most common form of familial ovarian cancer can be attributed to mutations in either of the BRCA1/2 genes, which account for 5-13% of ovarian cancer cases in Western countries and for half of the familial aggregation of this disease." (PMID 20167074, 2010). "Women who are notified they carry a BRCA1/2 mutation are presented with surgical options to reduce their risk of breast and ovarian cancer, including risk-reducing mastectomy (RRM) and risk-reducing oophorectomy (RRO)." (PMID 20687957, 2010). "BRCA1 is a tumor-suppressor gene in which germ-line mutations lead to a predisposition of breast and ovarian cancer." (PMID 20576130, 2010). "It is estimated that 60% of sporadic ovarian carcinomas and the majority of those diagnosed in BRCA1 mutation carriers are of the high-grade serous type." (PMID 20445756, 2010). "Prospectively observed survival of patients with BRCA1 mutations and with breast or ovarian cancer, is 50% or less in 10 years." (PMID 20180971, 2010). "Breast cancer susceptibility gene (BRCA) 1/2: BRCA1/2 play important roles in maintaining genomic stability and act as tumor suppressors in breast and ovarian cancer development." (PMID 23554638, 2010). "Ovarian cancers associated with germline mutations of BRCA1 appear to be predominantly of serous type and age of the patient at diagnosis is significantly less as compared to the sporadic ovarian cancers." (PMID 20350313, 2010). "Up to 10% of epithelial ovarian cancers (EOCs) are caused by germline mutations in the tumor suppressor genes, Breast Cancer 1 (BRCA1) and BRCA2." (PMID 20182637, 2010). "The increased risk of ovarian cancer was evident only for the relatives of known BRCA1 mutation carriers, and the increased risk of prostate cancer was evident only for the relatives of known BRCA2 mutation carriers." (PMID 20877337, 2010). "The 16 familial case patients who had breast or ovarian cancer and at least one relative with these cancers were analyzed for mutations in the BRCA1 and BRCA2 genes." (PMID 20380699, 2010). "It is well known that the germ-line mutation of BRCA1 predisposes women to early-onset breast and ovarian cancer." (PMID 20160719, 2010). "We have suggested that all incident cases of breast or ovarian cancer in Norway should be offered testing for the Norwegian deleterious BRCA1 and BRCA2 mutations." (PMID 20180971, 2010). "An inherited BRCA1-mutation confers an increased risk of ovarian cancer, with lifetime risk estimates ranging from 10-60%, compared to a risk of less than 2% for the general population." (PMID 20576130, 2010). "Ovarian cancer patients with tumors known to harbor a germline mutation in BRCA1 are believed to display a better response to platinum-based therapies and improved survival compared to patients without BRCA1-associated disease." (PMID 20182637, 2010). "Hereditary breast and ovarian cancer susceptibility gene product BRCA1, by binding to the promoter region of SIRT1, is a positive regulator of SIRT1 expression." (PMID 20160719, 2010). "Germline mutations in BRCA1/2 genes are responsible for a large proportion of hereditary breast and/or ovarian cancers." (PMID 24281179, 2010). "The lifetime risk of ovarian cancer for patients with BRCA1 mutations is 20% to 60%, and the risk for BRCA2 mutation carriers is 10% to 35%." (PMID 20350313, 2010). "The cumulative risk of ovarian cancer to age 70 years for women with a BRCA1 or BRCA2 mutation is estimated at about 40% and 10%, respectively." (PMID 20122277, 2010). "The lifetime risk of ovarian cancer for BRCA1 and BRCA2 mutation carriers is estimated at 40–50% and 10–20%, respectively." (PMID 20069122, 2010). "Different agents are undergoing phase I and II clinical trials in BRCA1/2-associated breast and ovarian cancer, and new compounds are entering in the early preclinical settings." (PMID 20877358, 2010). "Between 5 and 10% of all ovarian cancer cases are associated with inheriting a mutation in the BRCA1 or BRCA2 gene." (PMID 20069122, 2010).
ovarian carcinoma (continued). "Women found to have a deleterious germline mutation in the BRCA1 or BRCA2 gene are known to be at increased risk for ovarian cancer, with lifetime risk estimates ranging from 40% to 60%." (PMID 20445756, 2010). "These mutations increase the risk for developing ovarian cancer by 26% (BRCA1) and 10% (BRCA2) during a woman's life time." (PMID 23554638, 2010). "Molecular testing for BRCA1 founder mutations 300 T/G, 4153delA and 5382insC was conducted in 588 persons who reported at least one case of breast or ovary cancer among blood relatives." (PMID 21034437, 2010). "The aim of the current study was to investigate the clinical relationship between aromatase and increased risk of breast and ovarian cancer in BRCA1 mutation carriers." (PMID 19445691, 2009). "The limited number of families tested precluded investigating the possible influence of BRCA1/2 mutations on the observed dominant Mendelian mode of segregation of ovarian cancer in the current study of 1919 GRFOCR families." (PMID 19536330, 2009). "A significant portion of ovarian cancer (OC) cases is caused by germ-line mutations in BRCA1 or BRCA2 genes." (PMID 19338682, 2009). "For ovarian cancer, the known highly penetrant susceptibility genes (BRCA1 and BRCA2) are probably responsible for only 40% of the excess familial ovarian cancer risks, suggesting that other susceptibility genes of lower penetrance exist." (PMID 19543528, 2009). "Our data suggest that somatic loss of BRCA1 favourably influences survival similar to the improved survival in ovarian carcinomas associated with inherited BRCA1 mutations." (PMID 19602291, 2009). "For ovarian cancer the risk is 39% and 11%, in BRCA1 and BRCA2 mutation carriers by 70 years, respectively." (PMID 19656415, 2009). "In a 2003 report the risk of breast and ovarian cancer for Ashkenazi women with inherited mutations in the tumor suppressor genes BRCA1 and BRCA2 has been estimated." (PMID 19825178, 2009). "Mutations in BRCA1 are often seen in BRCA1-associated breast and ovarian cancers, indicating that genetic mutations in BRCA1 are linked to loss of function in Smad3-mediated TGF-β signaling." (PMID 19768112, 2009). "The ovarian cancer risk for BRCA1 and BRCA2 mutation carriers was 40% (95% CI, 35% - 46%) and 18% (95% CI, 13% - 23%) respectively." (PMID 19825178, 2009). "Among BRCA1 and BRCA2 mutation carriers, there is considerable variability in both the age at diagnosis and the incidence of breast and ovarian cancers, even among women who carry the same BRCA1 and BRCA2 mutation." (PMID 19843326, 2009). "Several PARP-1 inhibitors are currently in phase I or II of clinical monotherapy trials in BRCA1/BRCA2-deficient breast or ovarian cancers." (PMID 19319136, 2009). "Breast cancer 1 (BRCA1) encodes a tumour suppressor gene whose germ line mutations in women are associated with a genetic predisposition to breast and ovarian cancer." (PMID 19239705, 2009). "While this study was limited to ovarian cancers of serous histological type and to those arising in BRCA1 mutation carriers specifically, we believe that the results are relevant to other hereditary serous cancers and to sporadic ovarian cancers." (PMID 19636370, 2009). "We selected a group of fifteen BRCA1 mutation carriers belonging to 11 distinct high-risk breast and ovarian cancer families and for whom 10 different BRCA1 mutations were identified by direct sequencing." (PMID 19352458, 2009). "Although the lifetime risk of developing ovarian cancer is increased in women with germline mutations of BRCA1, previous studies in mice suggest that loss of Brca1 alone was insufficient to lead to the development of EOC." (PMID 20046879, 2009). "In one study, 6% of prophylactically removed ovaries from BRCA1 mutation carriers were found to harbor microscopic ovarian carcinomas." (PMID 20046869, 2009).
ovarian carcinoma (continued). "Most of the published investigations reported a correlation between the presence of BRCA1 mutation and family history of breast/ovarian cancer as well as earlier onset of the disease." (PMID 19338682, 2009). "Asp67Glu and Thr1051Ser are the two BRCA1 missense mutations which occurred in Thai familial breast/ovarian cancer patients." (PMID 19865540, 2009). "Presence of ovarian cancer in family increased the occurrence of BRCA1-2 germline mutations in either the subset of "high-risk" families (5/16; 31%) or the group of "no high-risk" families (1/8; 12.5%)." (PMID 19619314, 2009). "A recent case-control study included 779 jewish women affected by hereditary ovarian cancer who had undergone genetic testing for three Askhenazi founder mutations (BRCA1 185delAG, 5382insC; BRCA2 617delT)." (PMID 19825178, 2009). "In the same study, the lifetime risk of ovarian cancer was 54% for BRCA1 and 23% for BRCA2 mutation carriers." (PMID 19825178, 2009). "Regarding the controversial issue linking mutations of the 3′ end of the BRCA1 to lower incidence of ovarian cancer, our data show that ovarian cancer is indeed lower when mutations inflict the 3′ end of the BRCA1 gene." (PMID 19329713, 2009). "In any case this landmark study provides proof of principle that ovarian cancer arising in BRCA1/2 mutation carriers is a different disease." (PMID 19825178, 2009). "Most studies report improved survival in women with ovarian carcinomas associated with BRCA1 and BRCA2 mutations compared to women with sporadic ovarian carcinoma, consistent with increased sensitivity to platinum-based chemotherapy." (PMID 19602291, 2009). "There was evidence that mutations in the 3′ end of the BRCA1 gene (3′ to exon 13) were less likely to be associated with ovarian cancer." (PMID 19329713, 2009). "This study indicates that all ovarian cancer patients of Russian ethnic origin have to be screened for the presence of a few BRCA1 founder mutations (BRCA1 5382insC, BRCA1 185delAG, BRCA1 4153delA)." (PMID 19338682, 2009). "In a previous study, segregation analysis of 112 high risk ovarian cancer families found that BRCA1/2 mutations accounted for only about one half of familial ovarian cancer." (PMID 19536330, 2009). "For example, 90% of ovarian cancers were associated with mutations in the 5′ end of the BRCA1 gene, while only 10% were linked to mutations in the 3′ end." (PMID 19329713, 2009). "Of the 136 cases carrying a mutated BRCA1 gene, 79 women who developed breast and/or ovarian cancers were included in the analysis." (PMID 19329713, 2009). "Of the three hereditary ovarian cancer families studied, one had a deleterious mutation in the BRCA1 gene." (PMID 19656415, 2009). "BRCA1 mutation carriers have an earlier onset of ovarian cancer that is histologically high-grade serous adenocarcinoma." (PMID 19656415, 2009). "It is shown that different BRCA1 gene mutations have distinct effects that influence the age of onset of breast or ovarian cancer." (PMID 19329713, 2009). "Linkage to the BRCA1 gene exists in ∼80% of families with inherited risk of breast and ovarian cancer." (PMID 20046879, 2009). "BRCA1 gene mutations have been extensively studied in relation to breast and ovarian cancer susceptibility." (PMID 19329713, 2009). "Five to fifteen percent of ovarian cancers are thought to be due to hereditary factors and the majority of these can be attributed to germline mutations in the BRCA1 gene." (PMID 20046869, 2009).
ovarian carcinoma (continued). "Here we present a large breast-ovarian cancer family, where 3 sisters and 1 half-sister inherited maternal BRCA1 5382insC mutation while the remaining 2 sisters carried paternal BRCA1 1629delC allele." (PMID 19338681, 2009). "Eighteen (37%) of the ovarian carcinomas had germline or somatic BRCA1 mutations, or epigenetic loss of BRCA1." (PMID 18208621, 2008). "While one investigation of the PHB polymorphism in an ovarian cancer population has been previously reported, nothing is known about its' influence in women with predisposing mutations in the BRCA1 gene." (PMID 18397521, 2008). "Germline mutations in the gene encoding the RING protein BRCA1 are associated with the inherited predisposition for breast and ovarian cancer." (PMID 19007437, 2008). "Inherited mutations of BRCA1 (chromosome 17q21) have been linked to increased risk for breast and ovarian cancers." (PMID 18394172, 2008). "Controls were matched to cases by year of birth and BRCA1 mutation and were similar to cases with respect to potential ovarian cancer risk factors including year of birth, age at first live birth, age at menarche, BMI, parity, breastfeeding, and smoking." (PMID 18397521, 2008). "Women harboring BRCA1 germ line mutations have a high life time risk of developing ovarian cancer, ranging from 16% in specific ethnic groups to 63% in highly selected families with multiple affected individuals." (PMID 18397521, 2008). "The penetrance of ovarian cancer is much lower in IVS16-2A>G BRCA2 families than in BRCA1 families with a Ring domain missense mutation or the 1806C>T mutation." (PMID 18783588, 2008). "One thousand and ten unrelated high-risk probands with breast and/or ovarian cancer were analysed for the presence of a BRCA1 or BRCA2 gene mutation at the Masaryk Memorial Cancer Institute (Czech Republic) during 1999–2006." (PMID 18489799, 2008). "In the present study we investigated the effect of PHB 3'UTR polymorphism on the risk of ovarian cancer in BRCA1 mutation carriers." (PMID 18397521, 2008). "A total of 254 BRCA1 mutation carriers including 127 ovarian cancer cases and 127 unaffected controls were included in this study." (PMID 18397521, 2008). "Although we tested 13 of 74 patients with ovarian cancer for BRCA1 or BRCA2 mutations and found a mutation in 10 of the 13 patients with familial cancer, this result is not representative of the whole population of patients." (PMID 18268495, 2008). "To date, only three different BRCA1 mutations have been identified in Northern Finnish breast and/or ovarian cancer families." (PMID 18501021, 2008). "The variable penetrance of ovarian cancer in BRCA1 mutation carriers suggests that other genetic or environmental factors modify disease risk." (PMID 18397521, 2008). "This is the first study, however, to report that decreased PTEN expression levels are associated with ovarian carcinomas carrying BRCA1 mutations while increased PI3KCA copy number is associated with ovarian carcinomas with epigenetic loss of BRCA1." (PMID 18208621, 2008). "For BRCA1 mutation carriers, the ovarian cancer risk by the age of 70 years was estimated to be 33% for women born prior to 1920, rising to 36% for those born between 1920 and 1939, and then dropping to 34%." (PMID 18349832, 2008). "In this report we tested 145 breast and/or ovarian cancer families in Slovenia for BRCA1/2 gene mutations." (PMID 18783588, 2008). "We used the BRCA1 breast and ovarian cancer predisposing gene model for the validation of the accuracy and efficiency of our strategy." (PMID 18973698, 2008). "Whilst it is clearly interesting to know the effect of BRCA1/2 alone, women undergoing testing will want to know what their own specific risk of breast and ovarian cancer are, including that contributed by other potential "modifier" genes in their family." (PMID 18513387, 2008).